PTH (parathyroid hormone)
Diseases named in the same sentence as PTH in open-access papers (continued):
Sharing a sentence is not in itself a finding about the gene and the disease.
primary hyperparathyroidism (continued). "Both parathyroid hormone (PTH) and total calcium concentrations affect otolin-1 concentrations, implying that the calcium dysregulation caused by primary hyperparathyroidism may contribute to the otoconia breakdown and may be associated with inner ear disorders such as BPPV." (PMID 39456211, 2024). "However, our data provide an important direction for future research, since an elevated PTH is associated with both bone health deterioration and non-skeletal consequences even out of context of primary hyperparathyroidism." (PMID 39281298, 2024). "Biochemical evaluation demonstrated markedly elevated intact parathyroid hormone levels, consistent with primary hyperparathyroidism." (PMID 42099311, 2026). "Primary hyperparathyroidism (PHPT) is a prevalent endocrine disorder characterized by excessive secretion of parathyroid hormone (PTH), leading to significant complications." (PMID 41509026, 2026). "Primary hyperparathyroidism (PHPT) is the third most common endocrine disorder, caused by excess parathyroid hormone (PTH) production, leading to elevated serum calcium levels." (PMID 40060374, 2025). "Primary hyperparathyroidism typically occurs due to a functional adenoma in the parathyroid gland, leading to the overproduction of parathyroid hormone (PTH)." (PMID 40267007, 2025). "Primary hyperparathyroidism is the most common condition associated with SCC, due to hypersecretion of PTH, which leads to elevated serum calcium levels." (PMID 40291202, 2025). "Primary hyperparathyroidism is defined by autonomous PTH secretion by one or more abnormal parathyroid glands, which leads to increased serum calcium." (PMID 40362670, 2025). "Given her history of nephrolithiasis, a PTH test was conducted, revealing elevated levels at 116.7 pg/mL (normal: 15–68.3 pg/mL), suggesting primary hyperparathyroidism (PHPT)." (PMID 41001160, 2025). "Laboratory tests revealed elevated intact parathyroid hormone (PTH) at 163 pg/mL, indicating primary hyperparathyroidism." (PMID 40525079, 2025). "Primary hyperparathyroidism is an endocrine disorder characterized by the overproduction and release of PTH from one or more of the four parathyroid glands." (PMID 41347015, 2025). "Laboratory testing confirmed primary hyperparathyroidism, with elevated serum calcium and intact parathyroid hormone (PTH) levels." (PMID 40525079, 2025). "Laboratory evaluation showed hypercalcemia with a corrected calcium level of 13.1 mg/dL and elevated intact PTH (163 pg/mL), indicating primary hyperparathyroidism." (PMID 40525079, 2025). "Our findings highlight a complex relationship between PTH and vitamin D in primary hyperparathyroidism, especially in the often-underdiagnosed normocalcemic phenotype." (PMID 40362670, 2025). "Primary hyperparathyroidism (PHPT) is an asymptomatic, endocrine malignancy, in 80-90% cases is caused by hypersecretion of parathormone (PTH) due to tumorigenesis in parathyroid glands." (PMID 40496565, 2025). "Primary hyperparathyroidism (PHPT) is a common endocrine disorder characterized by parathyroid hormone (PTH) levels inappropriately elevated relative to serum calcium levels, typically due to overactivity in one or more parathyroid glands." (PMID 40502402, 2025). "Primary hyperparathyroidism (PHPT) is defined as long‐term excessive secretion of parathyroid hormone (PTH) as a result of an adenoma, hyperplasia, or, rarely, carcinoma." (PMID 40517023, 2025). "As the patient’s father passed away due to complications of peptic ulcers and hailed from a region with high rates of MEN1, PTH and calcium levels were checked, confirming the diagnosis of primary hyperparathyroidism (pHPT)." (PMID 40476723, 2025). "By contrast, primary hyperparathyroidism typically presents with more pronounced elevations in calcium and PTH levels, low serum phosphate levels, normal magnesium levels, and hypercalciuria." (PMID 40182382, 2025).
primary hyperparathyroidism (continued). "Primary hyperparathyroidism (PHPT) is an endocrine disease resulting from excess release of parathyroid hormone (PTH) from one or more of the parathyroid glands." (PMID 40263174, 2025). "PTH collection from the internal jugular veins is useful in patients with primary hyperparathyroidism who underwent surgery as a possible method of localization exams, indicating adenoma laterality." (PMID 40209343, 2025). "Key words:Parathyroid hormone, normocalcemic primary hyperparathyroidism, 25 OH vitamin D, periodontitis, bone density, periodontal diseases." (PMID 39582410, 2025). "Primary hyperparathyroidism is a condition characterized by an excessive production of parathyroid hormone primarily resulting from the presence of an adenoma or hyperplasia of the parathyroid glands." (PMID 40686699, 2025). "Further work-up revealed plasma intact parathyroid hormone (PTH) levels within the lower normal range, ruling out primary hyperparathyroidism." (PMID 39897231, 2025). "Key laboratory findings included markedly elevated intact PTH at 163 pg/mL (reference: 10-65 pg/mL) and corrected calcium at 13.1 mg/dL (reference: 8.8-10.1 mg/dL), confirming primary hyperparathyroidism." (PMID 40525079, 2025). "Primary hyperparathyroidism (PHPT) is the third major endocrine disorder characterized by increased secretion of parathyroid hormone, with an incidence of up to 3% in elderly women." (PMID 40660580, 2025). "There are several prior studies that have demonstrated a direct positive correlation between a high serum PTH or a high serum calcium and successful sestamibi localisation in patients with known primary hyperparathyroidism." (PMID 40979160, 2025). "Primary hyperparathyroidism (pHPT) secondary to solitary or multiple parathyroid adenomas is characterized by the persistent elevation of parathyroid hormone (PTH) and serum calcium levels." (PMID 41509929, 2025). "A retrospective analysis was conducted on 141 patients who underwent parathyroidectomy for primary hyperparathyroidism, focusing on the intraoperative drop in PTH and surgical success." (PMID 40637883, 2025). "In the course of primary hyperparathyroidism (pHPT) chronic excess parathyroid hormone (PTH) secretion results in abnormal calcium-phosphate homeostasis and bone dysmetabolism." (PMID 40771273, 2025). "Intraoperative parathyroid hormone (PTH) measurement is a beneficial tool in the surgical management of primary hyperparathyroidism." (PMID 40637883, 2025). "•The selective PTH collection from the jugular vein identified adenoma laterally in 75.86% of patients with primary hyperparathyroidism." (PMID 40209343, 2025). "Primary hyperparathyroidism (PHPT) is a condition characterized by the excessive secretion of parathyroid hormone (PTH) by the parathyroid glands, leading to elevated calcium levels." (PMID 40779536, 2025). "Overestimation of PTH by second-generation assays because of PTH fragment cross reactivity is of negligible consequence in patients with primary hyperparathyroidism." (PMID 40937300, 2025). "Primary hyperparathyroidism (PHPT) is a significant endocrine disorder characterized by the overproduction of parathyroid hormone (PTH), primarily affecting women in their 40s." (PMID 40539180, 2025). "Laboratory findings confirmed primary hyperparathyroidism, with elevated PTH levels of 187 pg/mL (SI: 187 ng/L) (reference range, 15-68.3 pg/mL [SI: 15-68.3 ng/L]) despite normal serum calcium levels." (PMID 40657234, 2025). "All CoEs screen patients for primary hyperparathyroidism (pHPT) with serum calcium measurement and, with the exception of three of the four Dutch CoEs, also with parathyroid hormone (PTH)." (PMID 39587981, 2025). "In primary hyperparathyroidism, the overproduction of PTH leads to increased bone resorption, which can result in the formation of cystic lesions filled with fibrous tissue and hemosiderin." (PMID 39997653, 2025).
primary hyperparathyroidism (continued). "Such a pattern is reminiscent of early-stage primary hyperparathyroidism, where PTH elevation can precede detectable changes in serum calcium and is associated with increased risk for bone remodeling abnormalities and bone loss." (PMID 40707943, 2025). "In more recent studies, 4D-CT has also been shown to be effective in cases of primary hyperparathyroidism (pHPT) with low PTH levels." (PMID 40807089, 2025). "Primary hyperparathyroidism (PHPT) is a medical condition in which parathyroid glands produce excessive parathyroid hormones (PTH)." (PMID 40104303, 2025). "Patients with increased PTH levels, calcium levels, and decreased phosphorus values were excluded from the study due to the possibility of primary hyperparathyroidism and were referred for endocrinologic consultation." (PMID 40313432, 2025). "In particular, for patients with primary hyperparathyroidism, further research is required to establish whether low vitamin D levels in this population reflect true deficiency or are a result of altered hepatic protein synthesis and enhanced conversion, modulated by PTH." (PMID 40362670, 2025). "Primary hyperparathyroidism (PHPT) is a common endocrine disorder characterized by excessive secretion of parathyroid hormone (PTH), most frequently due to a solitary adenoma." (PMID 41323977, 2025). "Primary hyperparathyroidism (PHPT) characterized by autonomous overproduction of parathyroid hormone (PTH) from one or more parathyroid glands." (PMID 41001670, 2025). "Screening for primary hyperparathyroidism should include annual plasma calcium and PTH measurements." (PMID 40136120, 2025). "Surgery, on the other hand, when indicated, normalizes PTH levels and reverses the end-organ effects of primary hyperparathyroidism while improving quality of life." (PMID 41210046, 2025). "Primary hyperparathyroidism (PHPT) is a disorder characterized by the overproduction of the parathyroid hormone (PTH)." (PMID 40686699, 2025). "There is no strict cut‐off value for serum calcium that definitively causes primary hyperparathyroidism (PHPT), as some cases are classified as normocalcemic PHPT, where serum calcium levels remain within the normal range despite elevated PTH." (PMID 41001160, 2025). "In patients with primary hyperparathyroidism and concurrent hypertension, parathyroidectomy often lowers blood pressure, possibly because excess PTH stimulates renin release and calcium–phosphate imbalance impairs endothelial relaxation." (PMID 41050279, 2025). "Primary hyperparathyroidism (PHPT) is an endocrine disease that results from the excessive production of PTH, leading to an imbalance between the osteoblast and osteoclast activity." (PMID 39997653, 2025). "Our study provides further insights regarding the complex interplay between PTH and vitamin D in primary hyperparathyroidism, with a particular emphasis on the normocalcemic phenotype, which remains prone to underdiagnosis and misclassification." (PMID 40362670, 2025). "Most people with primary hyperparathyroidism require surgery to remove the aberrant gland because they have increased serum levels of calcium and parathyroid hormone." (PMID 40119143, 2025). "As a common endocrine disorder, primary hyperparathyroidism (PHPT) stems from the autonomous production of the parathyroid hormone (PTH) and is characterized by several clinical and biochemical manifestations." (PMID 40217729, 2025). "Normocalcemic hyperparathyroidism (nPHPT) is a form of primary hyperparathyroidism (PHPT) where the patient has normal levels of calcium in the blood but elevated levels of parathyroid hormone (PTH)." (PMID 39610557, 2024). "Primary hyperparathyroidism (pHPT) emerges as a endocrine disorder, marked by the autonomous and excessive production of parathyroid hormone (PTH)." (PMID 38541233, 2024).
primary hyperparathyroidism (continued). "We report a case of a 48-year-old male patient who was referred to the endocrinology outpatient clinic due to elevated calcium (Ca) and elevated parathyroid hormone (PTH) levels, indicating primary hyperparathyroidism (PHPT)." (PMID 39712793, 2024). "Primary hyperparathyroidism (PHPT) is an endocrine disorder marked by an excessive production of parathyroid hormone (PTH), disrupting calcium metabolism." (PMID 39529989, 2024). "Primary hyperparathyroidism (PHPT) is a prevalent clinical condition characterized by an inappropriate secretion of parathyroid hormone (PTH)." (PMID 39845209, 2024). "Primary hyperparathyroidism was subsequently confirmed with parathormone (PTH) exceeding 2,500 pg/mL (12-88 pg/mL), leading to left-superior parathyroidectomy and hemithyroidectomy." (PMID 39478762, 2024). "In this study, all 37 patients with primary hyperparathyroidism underwent surgery and achieved a complete cure with normal serum PTH and SCa." (PMID 39247148, 2024). "Normocalcemic primary hyperparathyroidism (NPHPT) is characterized by normal calcemia despite elevated parathyroid hormone (PTH) levels." (PMID 39040613, 2024). "In patients even with a suggestive constellation of primary hyperparathyroidism, an ectopic paraneoplastic PTH source should be considered if the localization diagnostics are without abnormalities or if the PTH values are unusually high." (PMID 39703837, 2024). "Primary hyperparathyroidism (PHPT) is characterized by excessive secretion of parathyroid hormone (PTH), which disrupts calcium homeostasis and profoundly affects bone metabolism." (PMID 39588408, 2024). "Based on elevated parathyroid hormone levels and radiological findings, a diagnosis of primary hyperparathyroidism has also been made." (PMID 39290923, 2024). "Primary hyperparathyroidism occurs when a functional parathyroid gland tumor, usually a functional adenoma, autonomously produces excess parathyroid hormone (PTH)." (PMID 39834923, 2024). "Primary hyperparathyroidism (PHPT) is a prevalent endocrine disorder characterized by hypersecretion of parathyroid hormone (PTH), with the third prevalence to diabetes and thyroid disease." (PMID 38770646, 2024). "All patients with primary hyperparathyroidism, particularly those with low dietary calcium intake, should be advised not to restrict dietary calcium to prevent further increase in PTH levels." (PMID 39963179, 2024). "The initial laboratory investigation identified severely elevated serum calcium (3.6 mmol/L) levels consistent with a hypercalcemic crisis (HC) and parathyroid hormone PTH (47.6 pmol/L) due to primary hyperparathyroidism." (PMID 38391401, 2024). "Primary hyperparathyroidism (PHPT) is a disorder in which excessiveparathyroid hormone (PTH) is secreted from the parathyroid glands." (PMID 39700332, 2024). "BACKGROUND: Primary hyperparathyroidism (PHPT) is a endocrine disorder characterized by excessive secretion of parathyroid hormone (PTH) from parathyroid gland tumors." (PMID 38433540, 2024). "Ectopic PTH-secreting masses represent a rare entity but should be considered in individuals with unclear etiology of recalcitrant primary hyperparathyroidism." (PMID 39611185, 2024). "Primary hyperparathyroidism (PHPT) is a disorder in which excessive parathyroidhormone (PTH) is secreted from one or more of the parathyroid glands." (PMID 39700332, 2024). "Chronic elevations in PTH levels, such as those observed in primary hyperparathyroidism, can precipitate osteoporosis." (PMID 39200293, 2024). "Normal calcium and PTH levels exclude primary hyperparathyroidism, the most common manifestation of MEN1." (PMID 39685871, 2024). "Hyperplasia or adenomas of the parathyroid glands in over 95% of cases, causing primary hyperparathyroidism (PHPT), characterized by excessive secretion of parathyroid hormone (PTH)." (PMID 38892509, 2024).
primary hyperparathyroidism (continued). "Primary hyperparathyroidism (PHPT) is a common metabolic disorder sustained by tumors of the parathyroid glands which release excessive amounts of parathyroid hormone (PTH)." (PMID 39409111, 2024). "A minimally-invasive parathyroidectomy with intraoperative parathyroid hormone monitoring was performed in the case of a male with a large neck mass and symptomatic primary hyperparathyroidism." (PMID 38971030, 2024). "Primary hyperparathyroidism is characterized by excess secretion of PTH with respect to serum calcium concentration." (PMID 39611185, 2024). "Primary hyperparathyroidism (PHPT) is characterized by inappropriately high levels of parathyroid hormone (PTH)." (PMID 39594132, 2024). "Primary hyperparathyroidism (PHPT) is distinguished by an excessive secretion of parathyroid hormone (PTH) from one or more of the parathyroid glands, leading to a dysregulation of calcium homeostasis." (PMID 39519139, 2024). "Patients with primary hyperparathyroidism have elevated parathyroid hormone and calcium levels and are an interesting population to examine." (PMID 38129969, 2024). "Primary hyperparathyroidism (PHPT) is a disorder marked by chronic parathyroid hormone hypersecretion, which affects bone turnover and remodelling processes." (PMID 39610557, 2024). "Primary hyperparathyroidism can be diagnosed on the basis of clinical presentations, bone lesions, renal lithiasis, and high SCa levels with concomitant high levels of PTH." (PMID 39247148, 2024). "Although primary hyperparathyroidism represents a relatively common endocrinological disorder, ectopic PTH secretion is a rare entity that is less well described in literature." (PMID 39611185, 2024). "A common endocrine condition called primary hyperparathyroidism (PHPT), which affects calcium metabolism, causes mild or asymptomatic hypercalcemia and high or inappropriately normal parathormone (PTH) levels." (PMID 39610557, 2024). "For differential diagnosis, calcitonin (for medullary thyroid cancer), calcium and PTH values (for primary hyperparathyroidism), and paragangliomas-related assays are helpful." (PMID 38791947, 2024). "Primary hyperparathyroidism (PHPT) is commonly caused by parathyroid adenoma, often marked by high levels of serum calcium and PTH, nephrocalcinosis, and other systemic manifestations such as bone pain and renal dysfunction." (PMID 39822449, 2024). "Primary hyperparathyroidism is an endocrine condition in which the chief cells of a single parathyroid gland or multiple glands produce excessive parathyroid hormone (PTH)." (PMID 38449925, 2024). "Primary hyperparathyroidism (PHPT) is a disorder of mineral metabolism characterized by increased or unsuppressed levels of parathyroid hormone (PTH) due to excessive secretion from one or more abnormal parathyroid glands." (PMID 38772934, 2024). "Io-PTH monitoring shows that the reduction in rapid PTH after parathyroidectomy for SHPT is approximately similar to previous studies in patients with primary hyperparathyroidism." (PMID 37231458, 2023). "Biochemistry revealed a grossly elevated serum calcium, PTH, and serum alkaline phosphatase with low serum phosphorous, suggestive of primary hyperparathyroidism." (PMID 37909004, 2023). "Primary hyperparathyroidism is a condition characterized by excessive secretion of parathyroid hormone (PTH) due to an abnormality in the parathyroid glands." (PMID 40729208, 2023). "The objective of this study is to assess the diagnostic value of four-dimensional dynamic computed tomography (4D-CT) in localizing primary hyperparathyroidism (pHPT) in patients with low baseline PTH levels, compared to patients with high baseline PTH levels." (PMID 37627880, 2023). "The patient was found to have elevated serum calcium and PTH, raising suspicion for the diagnosis of primary hyperparathyroidism." (PMID 37609099, 2023).